HOXC6 (homeobox C6)
Diseases named in the same sentence as HOXC6 in open-access papers (continued):
Sharing a sentence is not in itself a finding about the gene and the disease.
tumor (55 papers, 2009 to 2026). "CAF-derived EVs deliver SNHG3 into CRC cells, where SNHG3 sponges miR-34b-5p to upregulate HuR and thereby enhance HuR’s association with HOXC6, increasing HOXC6 expression and driving tumor cell proliferation." (PMID 41200195, 2025). "What’s more, we further analyzed the tumor mutation signature between HOXC6 high and low groups and the result showed that the C> T mutation was the main type in both groups." (PMID 34950145, 2021). "In summary, overexpression of HOXC6 is likely to be associated with remodeling of the tumor immune microenvironment in CRC." (PMID 34950145, 2021). "We further determined the significance of HOXC6 in tumor cell migration and invasion, which has been implicated from clinical data." (PMID 29348394, 2018). "Supportively, evidence has demonstrated that HOXC6 gene has association with various tumor progressions." (PMID 30559605, 2018). "High HOXC6 expression was associated with primary tumor location in the right colon (P = 0.036), primary pT stage 3/4 (P < 0.001) and primary pN stage 1/2 (P < 0.001)." (PMID 27081081, 2016). "A detailed mechanism of how HOXC6 promotes metastasis in tumor cells may elucidate the association between high expression of HOXC6 and RCC aggressiveness." (PMID 33795652, 2021). "Our results and previous foundings imply that high HOXC6 expression is associated with tumor progression and may act as potential prognostic biomarker for HCC patients." (PMID 29348394, 2018). "Moreover, the prognostic significance of HOXC6 in different risk of subgroups according to tumor size, vascular invasion, TNM stage and BCLC stage was also assessed, which showed that HOXC6 could maintain its prognostic value in different risk of HCC patients." (PMID 29348394, 2018). "Consistent with the previous results, HOXB7 and HOXC6 showed significantly higher expression in tumor tissues as compared to the adjacent normal tissues." (PMID 39980564, 2025). "Quantitative analysis of tumor volumes at day 20 post subcutaneous implantation showed significantly reduced tumor sizes in the sh-HOXC6 group compared to the sh-NC group." (PMID 40574852, 2025). "Both in vitro and in vivo functional experiments showed that HOXC6 knockdown significantly inhibited tumor growth and metastasis, confirming its oncogenic role." (PMID 40574852, 2025). "To investigate the mechanisms by which HOXC6 promotes tumor progression, we performed transcriptome sequencing." (PMID 40255403, 2025). "Studies have reported that high expression of HOXC6 in CRC can promote tumor metastasis by activating the classical WNT pathway and promoting proliferation through the TGF-β/smad pathway." (PMID 39399504, 2024). "Tumor cell biology experiments verified the role of HOXC6 in proliferation and cell cycle progression." (PMID 35432534, 2022). "For HOXC6, seven and nine samples out of 16 exhibited strong staining in normal and tumor samples, respectively." (PMID 35836930, 2022). "For instance, the HOXC6 protein modulates cell differentiation during embryonic development, while aberrantly elevated HOXC6 expression levels are correlated with tumor progression." (PMID 35922404, 2022). "Regulating genes with both oncogenic and tumour suppressor activities, as well as several genes important for prostate morphogenesis and metastasis to the bone, HOXC6 is frequently overexpressed in patients with PCa." (PMID 35960727, 2022). "The protein levels of HOXC6 in other tumor groups were also higher than in the normal group, except for T9 and T10 samples." (PMID 35571491, 2022). "Differences in HOXC6 expression between tumour and normal tissues from patients with different cancers were detected by using data from the Oncomine database." (PMID 35488304, 2022). "High HOXC6 expression was related to high infiltration by immune cells, a low tumour purity score, a high stromal score, a high immune score and the expression of a variety of immune checkpoint genes, including PD-L1, B7-H3 and CLTA-4." (PMID 35488304, 2022).
tumor (continued). "Compared with the normal group, the protein levels of HOXC6 increased in the tumor groups, including groups T1, T2, T3, T4, T6, T7, and T11-T16." (PMID 35571491, 2022). "The results showed that the expression of HOXC6 was significantly positively correlated with these tumor immune microenvironment characteristics." (PMID 34950145, 2021). "An in vivo tumor formation mouse model by subcutaneous injection of stable HOXC6-OE and HOXC6-KD HCT116 cells demonstrated HOXC6 didn’t change tumor cell proliferation, which was in concordance with in vitro results." (PMID 33795652, 2021). "The activation of Wnt/β-catenin by HOXC6 provided potential therapeutic option for targeting upstream of Wnt/β-catenin pathway to inhibit tumor metastasis." (PMID 33795652, 2021). "HOXC6 expression was significantly increased in the majority of NSCLC tumor samples in as compared to healthy control lungs, which suggested HOXC6 as a novel biomarker for the diagnosis and treatment of NSCLC." (PMID 32830458, 2021). "Xenograft tumor in nude mice was used to determine the effects of miR-495 and HOXC6 on the tumor growth in vivo." (PMID 32171324, 2020). "Compared with the blank and NC groups, the miR-495 agomir and sh-HOXC6 groups displayed significantly decreased tumor volume and weight (p < 0.05)." (PMID 32171324, 2020). "A human tissue microarray containing 462 samples from CRC patients detected significantly higher HOXC6 expression in tumor tissues compared to matched normal mucosa (P<0.001), which also acted as an independent prognostic marker to poor overall survival." (PMID 33123277, 2020). "Next, HOXC6 expression was higher in CC tissues in comparison with that in neighbouring non‐tumour tissues." (PMID 32515533, 2020). "To validate these findings, we used qRT-PCR to determine HOXC6 expression in tumor samples from NSCLC patients." (PMID 30993034, 2019). "HOXC6 expression was significantly increased in 66.6% (20/30) of NSCLC tumor samples in comparison to normal controls." (PMID 30993034, 2019). "IHC analysis was consistent with the gene expression data, as HOXC6 protein was elevated in NSCLC tumor samples in comparison to adjacent normal controls." (PMID 30993034, 2019). "In 30 pairs of NSCLC tissue samples and adjacent non-tumor tissue samples, 66.6% (20/30) had elevated levels of HOXC6 in comparison to their adjacent normal counterparts (P = 0.01)." (PMID 30993034, 2019). "The relative HOXC6 mRNA expression level in tumor tissues was also significantly higher than in adjacent normal counterparts." (PMID 30886783, 2019). "The IHC score of HOXC6 in tumor tissues was significantly higher than in adjacent normal counterparts." (PMID 30886783, 2019). "Our functional studies found that HOXC6 had strong tumorigenicity, with overexpression of HOXC6 promoting tumor cell migration and invasion." (PMID 29348394, 2018). "As EMT is one of the key events in tumor invasion and metastasis, the effect of HOXC6 on EMT markers was analyzed." (PMID 29348394, 2018). "The role of HOXC6 in promoting tumor metastasis was further supported by the in vivo experimental metastasis assay." (PMID 29348394, 2018). "HOXC6 overexpression is capable of promoting colony formation and upregulating tumor growth factors, suggesting its important role in tumor growth." (PMID 30559605, 2018). "We further evaluated the effect of HOXC6 on tumor metastasis in SK-Hep1 and HuH7 xenografts in vivo." (PMID 29348394, 2018). "Patients with high HOXC6 expression more frequently received postoperative adjuvant chemotherapy (P = 0.055) because of higher tumor stage." (PMID 27081081, 2016). "Clinicopathologic data showed that increased HOXC6 expression is correlated with tumor location in the right colon and higher T and N stages." (PMID 27081081, 2016). "Only HOXC4 and HOXC6 showed consistently higher expression in the tumour compared to the normal prostate, with increases of 101 and 251 fold, respectively." (PMID 24499138, 2014).
tumor (continued). "Our confirmation of these relationships accentuates the question of how HOXC6 contributes to oncogenesis and tumor progression in the prostate." (PMID 24213107, 2011). "CCK-8 assays showed significantly reduced cell proliferation 24 hours post-treatment, while colony formation assays confirmed abemaciclib’s ability to markedly decrease colony numbers, indicating effective inhibition of tumor cell proliferation through HOXC6 targeting." (PMID 40574852, 2025). "Therefore, the outcomes of these experiments in vitro showed that HOXB7 and HOXC6 are key oncogenes that promote tumor malignant behavior and cell proliferation in LUAD cell lines." (PMID 39980564, 2025). "Previous studies have indicated that HOXC6 can regulate the tumor immune microenvironment." (PMID 40255403, 2025). "Interestingly, we also found that HOXC6 expression levels were higher in tumor cell lines than in the normal cell line on the basis of the GSE45544 dataset." (PMID 40255403, 2025). "Elucidating HOXC6’s EMT-regulatory mechanisms will advance understanding of tumor heterogeneity and may yield novel molecular classification systems and therapeutic targets for precision medicine." (PMID 40574852, 2025). "HOXC6 expression is significantly higher in tumor tissues than in normal tissues." (PMID 40255403, 2025). "Furthermore, HOXC6 was highly expressed in tumor tissues in the external validation cohort and maintained strong diagnostic efficacy, with an AUC of 0.966 (95% CI: 0.910−0.999)." (PMID 40255403, 2025). "Like PRAC1, HOXC6 specifically is frequently reported as one of the most differentially expressed genes, and, notably, has been linked to epithelial-to-mesenchymal transition (EMT) and tumor proliferation in various malignancies, including CRC." (PMID 40312719, 2025). "Therefore, HOXC6 is very likely to promote the functions of these tumour-infiltrating immunosuppressive cells." (PMID 35488304, 2022). "Since HOXC6 is a significant transcription factor in many tumours, ChIP-seq was performed." (PMID 35488304, 2022). "The functional network binding to hub genes indicated that the EMT signalling pathway may be the core pathway by which HOXC6 regulates tumour progression." (PMID 35488304, 2022). "Furthermore, high expression of HOXC6 was found to be significantly related to the tumor inflammatory microenvironment." (PMID 34950145, 2021). "In the HT29 cell line, a similar result was observed that tumor cells were more sensitive to irinotecan (P < 0.01, t-test), 5-FU + irinotecan (P < 0.01, t-test) and 5-FU + irinotecan+oxaliplatin (P < 0.05, t-test) by knockdown of HOXC6." (PMID 33795652, 2021). "Moreover, inhibited tumor growth was observed in vivo after injection with miR-495 agomir or sh-HOXC6." (PMID 32171324, 2020). "In comparison, expression of HOXC6 was observed in 181 (47.01%) of the tumor cases." (PMID 32745141, 2020). "We first investigated the expression of HOXC6 using clinical tumor samples." (PMID 30886783, 2019). "HOXC6 regulates genes with both oncogenic and tumor suppressor activities through the regulation of its functional biological targets bone morphogenic protein 7, platelet-derived growth factor receptor and fibroblast growth factor receptor 2, as well as PI3K/AKT, Notch and Wnt pathways." (PMID 29348394, 2018). "In the high tumor invasiveness group, patients with high HOXC6 expression were likely to death (P = 0.001) and recurrence (P < 0.001) compared with those with low HOXC6 expression." (PMID 29348394, 2018). "Our results revealed that co-index of HOXC6 expression and serum AFP level could be more beneficial for differentiating the risk of tumor survival and relapse of patients than HOXC6 expression or serum AFP alone." (PMID 29348394, 2018). "In general, HOXC6 status in HCC accelerating tumor progression reveals that HOXC6 may be a promising target in cancer therapy." (PMID 29348394, 2018).
tumor (continued). "In summary, our results showed that HOXC6 may promote tumor progression by inducing EMT pathway and can serve as a feasible prognostic predictor for HCC patients." (PMID 29348394, 2018). "Therefore, HOXC6 represents a potential factor affecting the tumour microenvironment." (PMID 35488304, 2022). "By evaluating its prognostic value, performing an in-depth bioinformatics analysis, and verifying with the tumor cell biology experiments, we showed that HOXC6 could predict the survival of GBM patients and that its expression correlated with the cell cycle-related genes." (PMID 35432534, 2022). "In addition, HOXC6, under the regulation of several signalling pathways, including the TGF-β pathway and Wnt pathway, is highly expressed and associated with promoting in tumours." (PMID 35488304, 2022). "To test this hypothesis, we first analysed the relationship between the HOXC6 expression level and tumour purity, which showed a negative association." (PMID 35488304, 2022). "Therefore, we further analyzed the correlation between HOXC6 overexpression and tumor immune microenvironment characteristics, including chemokine expression level, immune cell infiltration ratio, immune checkpoint expression level, TMB score, and MSI-H status." (PMID 34950145, 2021). "Taken together, these results suggest that HOXC6 may be a tumor growth-promoting oncogene." (PMID 27081081, 2016). "Multi-omics data and functional experiments systematically revealed the central regulatory role of HOXC6 in specific CRC subtypes, providing novel insights into tumor heterogeneity." (PMID 40574852, 2025). "This study aimed to evaluate the gene expression profiles of DKK1, HOXC6, and YKT6 in OSCC patients and explore their potential roles in tumour progression." (PMID 41477365, 2025). "RT-qPCR and IHC indicated that the expression of GLS, NOX1, HOXC6, TNNT1 and PLA2G12B were up-regulated in tumor tissues, compared with those in normal tissues, and all of GLS, HOXC6, NOX1 and PLA2G12B were closely related with patient survival." (PMID 37333810, 2023). "However, it remains unclear whether HOXC6 plays a role in tumor proliferation and metastasis." (PMID 33795652, 2021). "In our study, we show that HOXC4 and HOXC6 colocalize with HOXB13, which is present at high levels in both normal and tumor prostate tissue." (PMID 32012197, 2020). "In our study, the expression of HOXC6 was closely correlated with MMP-9 expression in HCC samples, suggesting that the tumor cells with high HOXC6 expression had high invasiveness." (PMID 29348394, 2018). "We revealed TFs whose expression is linked to a large number of tumor-specific enhancers and further characterized selected TFs for each tumor type (e.g., BRCA: GATA3, FOXA1, ESR1, PRAD: HOXC6, DLX1, KIRC: ZNF395) and for specific tumor subgroups." (PMID 27833659, 2016). "In total, our data uncovered important roles for CCND2, HOXC6 and PLXNA1 in regulating ERMS proliferation, validating the role of several novel genes in regulating continued tumor cell proliferation in human ERMS cells." (PMID 24009521, 2013). "HOXC6 has been reported to be highly expressed in human ERMS compared with ARMS, suggesting an possible role in modulating tumor growth." (PMID 24009521, 2013). "Furthermore, molecular docking revealed that the targeted agent abemaciclib effectively binds HOXC6, with both cellular and animal experiments confirming its ability to inhibit CRC cell functions and significantly reduce tumor burden in nude mice." (PMID 40574852, 2025).
tumor (continued). "Comparing benign to tumour samples, HOXA6 (p = 4.26 × 10−5), HOXB6 (p = 0.001), HOXC5 (p = 4.69 × 10−5), HOXC6 (p = 3.02 × 10−28), and HOXC9 (p = 0.0001) all showed significantly greater expression in tumour samples, with HOXC6 having by far the greater fold difference." (PMID 40725480, 2025). "Besides, we also evaluated the expression differences of HOXB7 and HOXC6 between tumor tissues and normal tissues in LUAD (based on log2(FPKM+1)), and both exhibit greater expression in tumor tissues with significant differences (p<0.001)." (PMID 39980564, 2025). "Furthermore, HOXC6 expression has also been related to the cellular composition of the tumor microenvironment (TME), with immune infiltration higher in patients with increased HOXC6 expression." (PMID 40312719, 2025). "Some researchers verified the role of CAFs-EVs containing SNHG3 in vivo by establishing a xenograft tumor model and found that SNHG3 promotes CRC cell proliferation by increasing HuR expression through the sponge miR-34b-5p and ultimately enhancing HOXC6 transcription." (PMID 39830506, 2024). "Moreover, ASCL2 was highly expressed in COAD compared with HOXC6 and APCDD1 in multiple tumor types." (PMID 35774798, 2022). "This means, CRC cells with high HOXC6 expression attract more CD8+ T cells by upregulating T cell attraction chemokines, however the tumor killing function of CD8+ T cells might be exhausted by downregulation of IFN- γ." (PMID 34950145, 2021). "Subsequently, gain- and loss-function approach was performed to detect the role of miR-495 and HOXC6 in cell proliferation, migration, invasion, cell cycle entry, apoptosis, and epithelial-mesenchymal transition (EMT) of CSCs in OSCC, as well as the tumor growth in vivo." (PMID 32171324, 2020). "We randomly selected three paired samples to analyze the expression level of the HOXC6 protein by western blotting, and the results showed that HOXC6 in tumor tissues was highly expressed when compared with adjacent normal counterparts." (PMID 30886783, 2019). "Because that EMT play an important role in tumor invasion and metastasis, and EMT can increase the invasion of cancer cells, we further detected whether the effect of HOXC6 on cell motility was via induction of the EMT pathway." (PMID 29348394, 2018). "We further investigated the effect of HOXC6 expression on prognosis independent of tumor invasiveness by using MMP-9 marker as an indicator for invasive potential of tumor cells." (PMID 29348394, 2018). "In this study, we found that the expression of HOXC6 in tumor was higher than that in adjacent non-tumorous tissues." (PMID 29348394, 2018). "LIMK1, HOXC6 and PLXNA1 represent potential novel candidate genes for driving tumor growth of ERMS." (PMID 24009521, 2013). "One plausible explanation for the paradox is that genes antagonizing tumor development become hypermethylated in prostate by independent mechanisms and are no longer accessible to transcriptional activation by HOXC6." (PMID 24213107, 2011). "To date, no studies have reported that HOXC6 mediates tumor progression by regulating ribosomes." (PMID 40255403, 2025). "However, as a miRNA generally has many target genes, whether other targets, such as FAM83D, HOXC6 and PBX3 and MEIS1 we mentioned, are involved in miR-495-mediated anti-tumor activity in NPC is still needed to be clarified." (PMID 35301291, 2022). "Although the HOXC6 protein expression levels were increased in GC tissues compared to the matched normal tissues, the results of relationship between tumor invasion depth and HOXC6 protein expression obtained were not statistically significant unlike HOXC6 mRNA expression." (PMID 32745141, 2020). "However, no obvious difference regarding tumor volume and weight was observed in the blank, NC, and miR-495 antagomir + sh-HOXC6 groups (p > 0.05)." (PMID 32171324, 2020). "Furthermore, HOXC6 overexpression was a factor for poor prognosis in patients with HCC independent of tumor cell invasiveness." (PMID 29348394, 2018).
tumor (continued). "Therefore, HOXC6 status may be a prognostic predictor for HCC patients independent of tumor invasiveness." (PMID 29348394, 2018).